CAV1 (caveolin 1)
Diseases named in the same sentence as CAV1 in open-access papers (continued):
Sharing a sentence is not in itself a finding about the gene and the disease.
age-related macular degeneration (3 papers, 2019 to 2025). Age-related loss of vision in the central portion of the retina (macula), secondary to retinal degeneration. "In age-related macular degeneration, the upregulation of both HMGB1 and CAV1 has been implicated in retinal pigment epithelium cell senescence." (PMID 40362460, 2025).
aneurysm (3 papers, 2015 to 2024). Bulging or ballooning in an area of an artery secondary to arterial wall weakening. "In our study, we not only found that CAV‐1 was down‐regulated in both rabbit and human aneurysms but demonstrated its association with the focal adhesion pathway." (PMID 33389819, 2021). "To determine the impact of Cav1 deletion on aortic root growth and aneurysm progression in male and female MFS mice, we measured the internal diameters of aortic rings isolated from mice." (PMID 39684412, 2024). "We also found that CAV‐1 is a ubiquitous gene that appears in almost every study of the rabbit aneurysm model." (PMID 33389819, 2021). "A mouse aneurysm model was used to show in vivo co-regulation of the smooth muscle differentiation marker calponin with caveolin-1 in the setting of vascular injury." (PMID 26244347, 2015). "Caveolin-1 (Cav1), a structural protein of plasma membrane caveolae, is known to inhibit eNOS activity, suggesting its involvement in MFS aneurysm progression by modulating NO levels." (PMID 39684412, 2024).
astrocytoma (3 papers, 2019 to 2023). "Empirical data now suggest that the rapid process extension of astrocytoma cells associated with glutamate signaling may involve kainic acid receptors (KARs) and/or CaV1 voltage-gated calcium channels." (PMID 36078065, 2022). "This study was undertaken to assess if Cav-1 expression in 1321N1 astrocytoma cells affects P2Y2R signaling and pro-survival actions after mechanical injury." (PMID 31635212, 2019). "To further establish the pathophysiological relevance of the Cav-1–P2Y2R interaction, we determined if caveolin-1 expression in 1321N1 astrocytoma cells impacted the P2Y2R signaling responses (ERK 1/2 and Akt) after mechanical injury." (PMID 31635212, 2019). "This study determines if Cav-1 knockdown (KD) affects P2Y2R signaling and its pro-survival actions in the 1321N1 astrocytoma cells mechanical injury model system." (PMID 31635212, 2019). "Collectively, the data demonstrate that Cav-1 is necessary for the P2Y2R-mediated signaling, pro-survival, and anti-apoptotic actions after mechanical injury in human 1321N astrocytoma cells." (PMID 31635212, 2019). "In the CNS, high-voltage CaVs were thought to be exclusive to excitable cells such as neurons (i.e., the CaV1 calcium channel family), but they are now known to also be expressed in non-excitable cells such as astrocytes and astrocytoma cells." (PMID 36078065, 2022). "In astroglial tumors, cytoplasmic dot-like, cytoplasmic and membrane, and intense membrane CAV1 staining are observed in grade II, III, and IV tumors, respectively, suggesting that CAV1 membrane expression is an indicator of the aggressiveness of tumors, such as astrocytomas and OSCC." (PMID 37047005, 2023).
B cell lymphoma (3 papers, 2015 to 2022). "As previously reported, higher CAV1 expression in B-cell lymphomas leads to a more aggressive disease with an inferior overall survival among patients with higher CAV1 expression." (PMID 26566034, 2015).
benign prostatic hyperplasia (3 papers, 2011 to 2019). A non-cancerous nodular enlargement of the prostate gland. "Although previous studies have found high level of Cav-1 from the serum of PCa patients compared with benign prostatic hyperplasia patients, further studies are needed to validate the applicability of TDEs in CRPC prognosis." (PMID 31685812, 2019).
cerebral microbleeds (3 papers, 2016 to 2024). Cerebral microbleeds are a group of pathological processes affecting the small arteries, arterioles, capillaries and venules of the brain, as detected by brain imaging techniques. "Circulating Cav‐1 concentration was positively correlated to cerebral microbleeds in acute ischaemic stroke patients, suggesting the role of Cav‐1 in vascular endothelial dysfunction." (PMID 38757755, 2024). "In a cross-sectional study, lower serum level of caveolin-1, which has been reported to maintain blood-brain barrier integrity and counteract oxidative stress, was found to be significantly related to cerebral microbleeds in patients with acute ischemic stroke." (PMID 27516831, 2016). "Though the relatively small sample size (~156 patients) may cripple the power of the evaluation, this study strongly supports caveolin-1 as a biomarker for predicting cerebral microbleeds in acute ischemic stroke." (PMID 27516831, 2016).
cerebral small vessel disease (3 papers, 2016 to 2025). Cerebral small vessel disease is the term currently used to pathological processes that affect the brain parenchymal circulation (arterioles, capillaries, and veins). "The present study aimed to investigate whether serum Cav-1 level is associated with the presence of cerebral small vessel disease (cSVD) in patients with acute ischemic stroke." (PMID 27119011, 2016). "Maintaining caveolin-1 level appeared to be a potential strategy in treating cerebral small vessel diseases." (PMID 27516831, 2016).
chronic kidney disease (3 papers, 2015 to 2025). Impairment of the renal function secondary to chronic kidney damage persisting for three or more months. "Strong upregulation of cav-1 has also been demonstrated in rodent models of chronic kidney disease and diabetic nephropathy." (PMID 30995923, 2019). "Of note, targeting Cav‐1 is also a promising therapeutic route in chronic kidney disease." (PMID 40616272, 2025). "Also, CAV1 genotyping may extend to other chronic kidney disease conditions in which CAV1 is thought to play a major role." (PMID 25945124, 2015).
chronic lung disease (3 papers, 2020 to 2025). According to the definitions of the American and British Thoracic Societies, including pulmonary functional tests, X-rays, and CT scans for items such as fibrosis, bronchiectasis, bullae, emphysema, nodular or lymphomatous abnormalities. "Cav‐1, especially altered DNA methylation patterns in the promoter region, was associated with chronic lung diseases." (PMID 32508059, 2020). "In conclusion, Cav‐1 is important in healthy and diseased lungs, of which the suppression of Cav‐1 expression and function may be associated with the pathogenesis of chronic lung disease." (PMID 32508059, 2020). "Combining with the evidences that Cav‐1 expression is significantly reduced in a variety of chronic lung diseases, we suspect that epigenetic changes of Cav‐1 may be a key pathological mechanism of chronic lung diseases." (PMID 32508059, 2020). "The regulation of Cav‐1 is multifunctional in chronic lung diseases." (PMID 32508059, 2020). "The changes in expression of Cav‐1 may be vital on chronic lung diseases as a new target for the treatment." (PMID 32508059, 2020). "The epigenetic changes in Cav‐1 may be a new target for the treatment of chronic lung diseases." (PMID 32508059, 2020).
diabetic cardiomyopathy (3 papers, 2024 to 2025). Diabetic cardiomyopathy is a disorder of the heart muscle in people with diabetes. "The ICM LV vs RV KEGG protein analysis revealed up-regulation of fluid sheer stress and diabetic cardiomyopathy principally due to the up-regulation of endothelial nitric oxide synthase 3 (NOS3, seven-fold), caveolin 1 (CAV1)." (PMID 39702518, 2024).
disc degeneration (3 papers, 2014 to 2023). "For instance, it was reported that caveolin-1 is upregulated with disc degeneration but not in association with age." (PMID 36719565, 2023). "However, the relationship between Cav1 and mechanical loading-induced disc degeneration or repair needs further investigation." (PMID 33867854, 2021).
endotoxemia (3 papers, 2017 to 2021). "Different from the outcome observed after LPS-induced endotoxemia, Cav-1−/− mice show a higher susceptibility to infections by Salmonella enterovar, displaying a higher bacterial burden in the spleen and liver compared to wild-type mice." (PMID 29250058, 2017). "After LPS-induced endotoxemia, the lungs of Cav-1−/− mice exhibit less neutrophil sequestration and edema formation." (PMID 29250058, 2017). "In conclusion, Cav-1−/− and Cav-2−/− mice show opposing outcomes in LPS-induced endotoxemia." (PMID 29250058, 2017).
gastritis (3 papers, 2013 to 2014). Inflammation of the stomach. "In gastritis with IM tissues, Cav-1 staining mainly locates in the absorptive cell and goblet cell of metaplastic glands." (PMID 23527097, 2013). "Our data showed that Cav1 protected B6129 mice against H. pylori-related gastritis and tissue damage in vivo independently of CagA." (PMID 23592983, 2013). "Instead, the gastritis was markedly enhanced in H. pylori-infected Cav1-KO mice compared with infected WT mice." (PMID 23592983, 2013). "In this study, we describe a novel role for Cav1 in H. pylori-mediated gastritis and cell damage." (PMID 23592983, 2013). "Nevertheless, our major objective was to present a first description of a beneficial role for Cav1 in H. pylori-related diseases, against gastritis in vivo and cytoskeletal stress in vitro, rather than to elaborate on the potential virulence mechanisms of SS1." (PMID 23592983, 2013). "In gastritis without IM tissues, Cav-1 signal is predominantly detected in the base and neck of fundic gland cells." (PMID 23527097, 2013). "In epithelial compartment, 30% (6/20) of gastritis without IM, 55% (11/20) of gastritis with IM, 75% (15/20) of GC were scored 0,showing Cav-1 protein expression level decreasing gradually." (PMID 23527097, 2013). "The localization and expression of Cav-1 in gastritis without IM, gastritis with IM and GC were assessed by QDs-IHC using the Cav-1 polyclonal antibody." (PMID 23527097, 2013). "Quantum dots immunofluorescence histochemistry was performed to examine the expression of Cav-1 in 20 cases of gastritis without intestinal metaplasia (IM), 20 cases of gastritis with IM and 286 cases of GC." (PMID 23527097, 2013). "Positive rates of epithelial Cav-1 in gastritis without IM, gastritis with IM and GC showed a decreasing trend (P = 0.012)." (PMID 23527097, 2013). "In gastritis with IM tissues, some cases showed no Cav-1 distribution and some showed positive Cav-1 staining in the absorptive cell and goblet cell of metaplastic glands." (PMID 23527097, 2013). "Friedman test showed that the difference of Cav-1 staining score between gastritis without IM, gastritis with IM and GC was statistically significant (P = 0.012)." (PMID 23527097, 2013). "In gastritis without IM tissues, negative Cav-1 signal predominantly in the surface mucous cells and positive signal predominantly in the base and neck of fundic gland cells." (PMID 23527097, 2013).
genetic lipodystrophy (3 papers, 2022 to 2025). "Certain forms of genetic lipodystrophy (e.g. mutations in CAV1 and PTRF) selectively lose peripheral WAT but preserve MAT." (PMID 36861967, 2023). "CAV-1, one of the genes considered in this study, is a principal regulator of fat distribution and genetic lipodystrophy in humans." (PMID 40628909, 2025). "It has been established by previous studies that CAV-1 has a major regulator function in fat distribution and genetic lipodystrophies in humans." (PMID 35641515, 2022).
head and neck cancer (3 papers, 2017 to 2022). A primary or metastatic malignant neoplasm affecting the head and neck. "CAV1 deletion cells displayed enhanced EMT and premetastatic properties in head and neck carcinoma." (PMID 36147736, 2022).
hyperlipidemia (3 papers, 2014 to 2025). "The lack of adiponectin exacerbates lipoatrophy and hyperlipidemia, and this may be due–at least in part–to the diminished insulin signaling and the selective loss of the caveolin-1 complex." (PMID 25339419, 2014).
idiopathic pulmonary arterial hypertension (3 papers, 2007 to 2015). A sporadic form of pulmonary arterial hypertension (PAH) characterized by elevated pulmonary arterial resistance leading to right heart failure. "Interestingly, they observed increased eNOS activity and PKG nitration concomitant with decreased Cav-1 expression in lung tissues from idiopathic pulmonary arterial hypertension patients compared with normal lungs in the absence of marked changes of eNOS and PKG expression." (PMID 26605130, 2012).
infarction (3 papers, 2019 to 2022). A localised pathological necrosis of tissue resulting from obstruction of the blood supply usually by a thrombus, an embolus, or vascular torsion. "Compared with the AMI group, BHD promoted the expression of Cav-1, VEGF, VEGFR2, and p-ERK in the infarction border zone after AMI." (PMID 31178960, 2019). "In the present study, BHD increased angiogenesis and the expression of Cav-1 in the infarction border zone, suggesting that the cardioprotective effect of BHD targeted angiogenesis by Cav-1." (PMID 31178960, 2019). "Recent studies showed that the expression of Cav-1 and VEGF was significantly decreased after the use of the caveolin-1 inhibitor, resulted in increase in neurological deficit and infarction volume." (PMID 31178960, 2019).
intracerebral hemorrhage (3 papers, 2016 to 2022). A cerebrovascular disorder characterized by bleeding into one or both cerebral hemispheres including the basal ganglia and the cerebral cortex. "CAV-1 is mainly upregulated in endothelial cells within the perihaematomal area of intracerebral haemorrhage." (PMID 36253854, 2022). "In an intracerebral hemorrhage model, Cav-1-knockout mice show smaller injuries, less brain edema, and less neuronal death compared with wild-type mice." (PMID 27708218, 2016).
kidney cancer (3 papers, 2018 to 2021). Primary or metastatic malignant neoplasm involving the kidney. "High levels of caveolin-1 expression can also be seen in hand and neck squamous cell carcinoma and kidney cancer cells that have metastasized." (PMID 30424755, 2018).
large cell lung carcinoma (3 papers, 2017 to 2023). "Also, patients with a large-cell lung cancer tumor showed a high stromal CAV1 expression (55.6%)." (PMID 29850392, 2018).
leiomyoma (3 papers, 2011 to 2021). A well-circumscribed benign smooth muscle neoplasm characterized by the presence of spindle cells with cigar-shaped nuclei, interlacing fascicles, and a whorled pattern. "Perivascular Cav-1 expression is considered as a marker for distinguishing benign from malignant uterine smooth muscle tumors given that perivascular Cav-1 is more expressed in leiomyosarcomas compared with uncertain malignant potentials and leiomyomas." (PMID 31759347, 2019). "The immunoreactivity for Cav-1 is observed in most cells of leiomyomas." (PMID 31759347, 2019). "Moreover, levels of CAV1, comparable to normal mesenchymal cells, were retained in all benign mesenchymal tumors, including 5 of 5 fibromatoses, 7 of 7 leiomyomas, 4 of 4 lipomas, and 6 of 6 hemangiomas." (PMID 21471610, 2011).
liposarcoma (3 papers, 2011 to 2019). A usually painless malignant tumor that arises from adipose tissue. "We also found differences in mRNA expression of caveolin-1 and flotillin-1 between liposarcomas and other mesenchymal tumors (p < 0, 05, χ2-test)." (PMID 24533441, 2014). "More importantly, SR-B1 and caveolin-1 protein may be play a role in the occurrence and development of liposarcoma together." (PMID 31413752, 2019). "In conclusion, SR-B1 and caveolin-1 may be co-located in liposarcoma, especially well-differentiated liposarcoma, which is related to the degree of cell differentiation of liposarcoma." (PMID 31413752, 2019). "Further studies have found that the expression of caveolin-1 is not only related to the degree of tumor cell differentiation, but also may represent a key step in the progression of liposarcoma tumorigenesis." (PMID 31413752, 2019).
lymphoma (3 papers, 2014 to 2022). A malignant (clonal) proliferation of B- lymphocytes or T- lymphocytes which involves the lymph nodes, bone marrow and/or extranodal sites. "By targeting specific CaV1 channels and, by extension, the mechanisms associated with each channel, this could lead to updated strategies to treat lymphoma." (PMID 35685639, 2022). "Using the top-scoring pairs method, the expression differential between CAV1 and BCL10 identified lymphoma samples with 98.4% sensitivity and 88.5% specificity." (PMID 26566034, 2015).
mastitis (3 papers, 2020 to 2025). Inflammation of breast tissue during lactation or postpartum due to an obstructed duct or infection. "Caveolin 1 contributes to ion homeostasis by regulating calcium influx and signal transduction and plays a role in mastitis by modulating leukocyte homeostasis and inflammatory responses." (PMID 40563467, 2025). "Additionally, some of the highly connected genes belonging to this module have been found by others to be related to mastitis development, immune response or mammary gland development including FYN, CDH11, CAV1, F11R, ZEB1, ERBB2, and ERBB3." (PMID 32754201, 2020).
mesenchymal tumors (3 papers, 2011 to 2021). "Of special interest, in our opinion, are the results indicating that benign and malignant mesenchymal tumors differ by caveolin-1 expression." (PMID 24533441, 2014). "A differential diagnostic method with IHC staining using a combination of several monoclonal antibodies against LMP2/β1i and other candidate cellular factors, such as caveolin 1, cyclin B, cyclin E, Ki-67/MIB1, and CD44, has been investigated for uterine mesenchymal tumors, including uLMS." (PMID 34563053, 2021).
mucoepidermoid carcinoma (3 papers, 2012 to 2021). A carcinoma morphologically characterized the presence of cuboidal mucous cells, goblet-like mucous cells, squamoid cells, cystic changes, and a fibrotic stromal formation. "Studies of salivary gland tumors found that caveolin-1 expression was inversely correlated with the duration of the tumor, clinical stage, histologic grade, and microvascular density in mucoepidermoid carcinoma and with the proliferation index in pleomorphic adenomas." (PMID 33037799, 2021).
muscular dystrophy (3 papers, 2016 to 2025). Muscular dystrophy (MD) refers to a group of more than 30 genetic diseases characterized by progressive weakness and degeneration of the skeletal muscles that control movement. "In addition, Cav3 deficiency causes muscular dystrophy but does not induce compensatory upregulation of Cav1." (PMID 41030451, 2025).
normal tension glaucoma (3 papers, 2012 to 2016). "Further studies are warranted to investigate the associations of the CAV1/CAV2 SNPs with normal-tension glaucoma, which will further enrich our understanding of the roles of the CAV1/CAV2 locus in POAG." (PMID 27297022, 2016). "We observed expression of seven genes which were previously genetically associated with POAG (included normal tension glaucoma (NTG)), namely APOE, CAV1, EDNRA, MYOC, OPTC and TMCO1." (PMID 23028713, 2012).
ovarian tumours (3 papers, 2008 to 2021). "Given that only malignant (or benign) cases were assessed, future studies should be undertaken to explore the utility of Cav-1 in more diagnostically challenging, “borderline” ovarian neoplasms." (PMID 34813586, 2021). "Taken together, these observations suggest a correlative link between PDK1, c-myc, PKCα and caveolin-1 in ovarian tumours and are consistent with those observed in mammary epithelial cell models." (PMID 18349831, 2008).